MIR1470 (microRNA 1470)
Synonyms: hsa-mir-1470; MIRN1470
Gene: MicroRNA gene on chromosome 19 (15,449,548 to 15,449,608, forward strand). Ensembl gene ENSG00000269782.
Homologues: Orthologues: chimpanzee MIR1470 (100% identical).